MIDEAS-AS1 (MIDEAS antisense RNA 1)
Gene: Long non-coding RNA gene on chromosome 14 (73,787,350 to 73,803,628, forward strand). Ensembl gene ENSG00000259065.
Diseases named in the same sentence as MIDEAS-AS1 in open-access papers:
MIDEAS-AS1 is named in the same sentence as 2 diseases in open-access papers, as found by Europe PMC text mining. Sharing a sentence is not in itself a finding about the gene and the disease.
MIDEAS-AS1 shares sentences with these, for which no sentence is quoted: breast carcinoma (1 paper); tumor (1).